TRIM24 (tripartite motif containing 24)
Diseases named in the same sentence as TRIM24 in open-access papers (continued):
Sharing a sentence is not in itself a finding about the gene and the disease.
infection (15 papers, 2016 to 2025). The state of being infected such as from the introduction of a foreign agent such as serum, vaccine, antigenic substance or organism. "TRIM28 and TRIM33 are known to form a trimeric complex with TRIM24, which itself was found (above) to reduce in abundance in lytic infection." (PMID 37410772, 2023). "During early infection, transcriptional factors associated with negative regulation of immune function, including IL1RN, SOCS1, and TRIM24 were downregulated." (PMID 33806942, 2021). "Similarly, the rAd-Cap infection promoted the interaction of TRIM24 with pNPM1 compared with the rAd-blank infection." (PMID 38394330, 2024). "Three days post infection with RBH we depleted TRIM24 by addition of doxycycline, and cells were left untreated, or stimulated with PMA and ionomycin; the infected cells were analyzed for latently and productively infected cells the following day by flow cytometry." (PMID 36690785, 2023). "Similar to the observations in N67 infection, IL10R, SOCS1, TRIM24, and PTGER2 were also inhibited in mice day 1 infected with 17XNL." (PMID 30327482, 2018). "IL1RN, MAPK1, TRIM24 and NKX2-3 were inhibited during infection in both classes, with significantly more inhibition in the ΔNF class relative to the ΔEF class." (PMID 27506615, 2016). "Together the results suggest that the interaction of BZLF1 with TRIM33 and TRIM24 in the context of lytic infection triggers phosphorylation and SUMOylation of TRIM33, as well as disruption of the TRIM complex, resulting in destabilization of TRIM24 and TRIM33." (PMID 37410772, 2023). "Knockout of either TRIM24 or TRIM33 significantly increased EBV genome amplification, with TRIM33 having the larger effect, likely because TRIM24 levels would already be low at this point in infection." (PMID 37410772, 2023). "In addition, a small group of transcription factors was predicted to be inhibited only upon infection with amastigotes (SOX6, RUNX3, and STAT1) or promastigotes (TRIM24, SIRT1, and FOXP3)." (PMID 35430587, 2022). "However, the activation values for TRIM24, a negative regulator of the IFN/STAT pathway, were found diminished after infection with both IFNα/βBP mutant viruses compared to WT virus." (PMID 30575728, 2018).
cardiac disease (2 papers, 2018 to 2025). "Our findings establish TRIM24 as a novel regulator of chromatin remodeling and cardiomyocyte transcription, directly influencing calcium homeostasis and contractility, with potential implications for cardiac disease." (PMID 40598158, 2025).
haematological disorder (2 papers, 2018 to 2020). "In addition, PROTACs targeting tripartite motif-containing protein 24 (TRIM24), receptor-interacting protein kinase 2 (RIPK2), and the Janus kinase family enzymes for degradation may also have the potential to be used to treat certain types of hematologic malignancies but require further studies." (PMID 32718354, 2020).
TRIM24 also shares sentences with these, for which no sentence is quoted: dermatomyositis (17 papers); myositis (13); acute promyelocytic leukemia (2); Bladder (2); calcinosis (2); clear cell renal cell carcinoma (2); interstitial lung disease (2); lymphoma (2); myelodysplastic syndrome (2); Obesity (2); polymyositis (2); small cell lung carcinoma (2); acute erythroid leukemia (1); adenocarcinoma (1); Adult onset (1); alcohol abuse (1); autoimmune disease (1); bone cancer (1); bowel cancer (1); brain cancer (1); cerebellar agenesis (1); Cirrhosis (1); CNS Tumors (1); colitis (1); colorectal adenocarcinoma (1); connective tissue disorder (1); depression (1); developmental verbal dyspraxia (1); Dystonia (1); Erythema (1).
A further 33 diseases each share a sentence with TRIM24 in 1 paper.